DST (dystonin)
Description:
Cytoskeletal linker protein. Acts as an integrator of intermediate filaments, actin and microtubule cytoskeleton networks. Required for anchoring either intermediate filaments to the actin cytoskeleton in neural and muscle cells or keratin-containing intermediate filaments to hemidesmosomes in epithelial cells. The proteins may self-aggregate to form filaments or a two-dimensional mesh. Regulates the organization and stability of the microtubule network of sensory neurons to allow axonal transport. Mediates docking of the dynein/dynactin motor complex to vesicle cargos for retrograde axonal transport through its interaction with TMEM108 and DCTN1 (By similarity). [Isoform 3]: Plays a structural role in the assembly of hemidesmosomes of epithelial cells; anchors keratin-containing intermediate filaments to the inner plaque of hemidesmosomes. Required for the regulation of keratinocyte polarity and motility; mediates integrin ITGB4 regulation of RAC1 activity. [Isoform 6]: Required for bundling actin filaments around the nucleus. [Isoform 7]: Regulates the organization and stability of the microtubule network of sensory neurons to allow axonal transport.
Synonyms: BPA; BP240; BPAG1; DMH; DT; KIAA0728; FLJ21489; FLJ13425; FLJ32235; FLJ30627; CATX-15; MACF2; CATX15; CMYO29; D6S1101; EBS3; EBSB2; HSAN6; LCCS12
Tractability: Antibody: UniProt places it where antibodies can reach, with medium confidence; its Gene Ontology location is reachable by antibodies, with medium confidence. PROTAC: UniProt records ubiquitination sites on it; ubiquitination databases record sites on it; its protein half-life has been measured.
Gene: Protein-coding gene on chromosome 6 (56,457,987 to 56,954,830, reverse strand). Ensembl gene ENSG00000151914.
Subcellular location: Cytoplasm, cytoskeleton; Cytoplasm, cytoskeleton, stress fiber; Cell projection, axon; Cytoplasm, cytoskeleton (Isoform 1); Cytoplasm, myofibril, sarcomere, Z line; Cytoplasm, myofibril, sarcomere, H zone; Cytoplasm, cytoskeleton (Isoform 2); Cytoplasm, cytoskeleton (Isoform 3); Cell junction, hemidesmosome; Nucleus (Isoform 6); Nucleus envelope; Membrane; Endoplasmic reticulum membrane; Cytoplasm, cytoskeleton (Isoform 7); Cytoplasm, cytoskeleton (Isoform 8); Cytoplasm, cell cortex; Cell membrane
Subcellular location (Human Protein Atlas): Microtubules; Nucleoplasm; Cytosol
Pathways (Reactome):
Signal Transduction: RHOU GTPase cycle; RHOV GTPase cycle; RND1 GTPase cycle; RND2 GTPase cycle; RND3 GTPase cycle
Cell-Cell communication: Type I hemidesmosome assembly
Extracellular matrix organization: Assembly of collagen fibrils and other multimeric structures
Gene Ontology:
Molecular function: integrin binding; microtubule plus-end binding; protein binding; microtubule binding; structural molecule activity; calcium ion binding; protein homodimerization activity
Biological process: cell motility; cytoskeleton organization; intermediate filament cytoskeleton organization; maintenance of cell polarity; response to wounding; integrin-mediated signaling pathway; retrograde axonal transport; wound healing; microtubule cytoskeleton organization
Cellular component: cell leading edge; cytoplasm; cytoplasmic vesicle; focal adhesion; microtubule plus-end; nucleus; basal plasma membrane; basement membrane; cytosol; endoplasmic reticulum membrane; hemidesmosome; intermediate filament; membrane; actin cytoskeleton; axon; axon cytoplasm; cell cortex; cytoskeleton; H zone; intermediate filament cytoskeleton; microtubule cytoskeleton; nuclear envelope; plasma membrane; polymeric cytoskeletal fiber; stress fiber; and 1 more
Genetic constraint (gnomAD): Loss-of-function variants: 197 observed, 747.14 expected, observed/expected ratio (o/e) 0.26, 90% interval 0.23 to 0.3. The upper end of that interval is the gene's LOEUF score, 0.3, which puts it in group 1 of 6, group 1 being the genes least tolerant of losing a copy. Missense variants: 7,632 observed, 8,636.3 expected, observed/expected ratio (o/e) 0.88, 90% interval 0.87 to 0.9. Synonymous variants: 2,870 observed, 3,071.7 expected, observed/expected ratio (o/e) 0.93, 90% interval 0.9 to 0.96.
Gene-disease validity (ClinGen):
ClinGen rates the evidence that DST causes each of these diseases.
hereditary sensory and autonomic neuropathy type 6 (autosomal recessive): Definitive. Any hereditary sensory and autonomic neuropathy in which the cause of the disease is a mutation in the DST gene.
Homologues: Orthologues: macaque DST (97% identical), chimpanzee DST (94% identical), dog DST (84% identical), pig DST (82% identical), mouse Dst (80% identical), rat Dst (80% identical), rabbit DST (68% identical), guinea pig DST (62% identical), tropical clawed frog dst (56% identical), zebrafish DST (31% identical), zebrafish si:ch211-165e15.1 (7% identical). Paralogues in human: MACF1 (44% identical), SYNE1 (14% identical), PLEC (13% identical), SYNE2 (11% identical), DMD (7% identical), SPTBN1 (7% identical), UTRN (7% identical), SPTBN2 (7% identical), SPTB (7% identical), SPTBN5 (7% identical), SPTBN4 (7% identical), DSP (6% identical), and 24 more.
Diseases named in the same sentence as DST in open-access papers:
DST is named in the same sentence as 98 diseases in open-access papers, as found by Europe PMC text mining. Sharing a sentence is not in itself a finding about the gene and the disease. The quoted sentences say what the papers report.
bullous pemphigoid (66 papers, 2010 to 2026). Bullous pemphigoid (BP) is the most common form of autoimmune bullous dermatosis. "Bullous pemphigoid is a rare autoimmune disease in which autoantibodies target hemidesmosomal proteins dystonin-e (BP antigen 1 or BP230) and collagen XVII (BP antigen 2 or BP180), causing basement membrane destruction and tense subepithelial bullae with pruritus." (PMID 38353200, 2023). "While the epithelial isoform dystonin-e/Bpag1e acts as an autoantigen in the human skin blistering disease bullous pemphigoid, the loss of function of dystonin neuronal and muscle dystonin/Bpag1 isoforms are associated with the dt phenotype and underlying pathology in the mouse mutant." (PMID 21698255, 2011). "Bullous pemphigoid (BP), the most common AIBD, is caused by autoantibodies against two hemidesmosomal proteins, BP180 (BPAG2, type XVII collagen) and BP230 (BPAG1, dystonin)." (PMID 40003627, 2025). "Dystonin/BPAG1 (DST) is bullous pemphigoid antigen 1, involving the autoimmune response in the development of bullous pemphigoid." (PMID 34116676, 2021).
breast carcinoma (11 papers, 2011 to 2025). "Five variants were in genes which have been reported to be associated with breast cancer risk in at least 50 manuscripts in PubMed (DST, CHEK2, FASN, TNN, and PMS2)." (PMID 38136396, 2023). "In this report, we demonstrate that Dystonin is a candidate tumour suppressor in breast cancer and provide an underlying molecular mechanism." (PMID 31882643, 2019). "To understand the contribution of DST in breast cancer cells, we first confirmed that transformation of the inducible MCF10A-ER-Src cell line was associated with the downregulation of DST." (PMID 31882643, 2019).
melanoma (11 papers, 2010 to 2025). A malignant, usually aggressive tumor composed of atypical, neoplastic melanocytes. "DST encodes a barrier protein that supports melanoma cell growth in vitro and in vivo, likely by interfering with immune cell infiltration or by enhancing angiogenesis." (PMID 35892849, 2022). "The barrier molecule junctions plakoglobin, filaggrin, and dystonin play roles in melanoma growth and angiogenesis." (PMID 38255907, 2024). "Dystonin plays an important role in tumor growth and angiogenesis of melanoma." (PMID 34354842, 2021). "Interestingly, dystonin expression identified a subset of melanoma patients with no CD8+ gene signatures." (PMID 37284199, 2023).
autoimmune disease (8 papers, 2015 to 2025). A disorder resulting from loss of function or tissue destruction of an organ or multiple organs, arising from humoral or cellular immune responses of the individual to their own tissue constituents. "Gene set analysis of the 100 most significant genes in the DNAemia meta-analysis found significant enrichment of genes associated with autoimmune disease of skin and connective tissue (DOID:0060039: FDR = 0.02; TG, DSG1,DST, LAMA3, HLA-DRB1)." (PMID 38005904, 2023).
Dystonia (6 papers, 2011 to 2023). An abnormally increased muscular tone that causes fixed abnormal postures. "Mutation/deletion of the gene (Dst) encoding dystonin in mice results in a dystonic movement disorder termed dystonia musculorum, which resembles aspects of dystonia in humans." (PMID 22611399, 2012). "Dystonia musculorum (dt) is a mouse inherited sensory neuropathy caused by mutations in the dystonin gene." (PMID 21698255, 2011). "The second mammalian spectraplakin, MACF2 or dystonin, is best known for its role in the neurological disorder dystonia." (PMID 26969328, 2016). "Loss of dystonin results in ultimately fatal peripheral neuropathies, namely hereditary sensory and autonomic neuropathy type VI (HSAN-VI) in humans and dystonia musculorum (Dstdt) in mice, characterized by ataxia, dystonic muscle and sensory neuron degeneration." (PMID 26886550, 2016). "A subset of FS symptoms, such as dystonia, myoclonus, and ataxia, may be attributed to the downregulation of PLEKHG2, DST, ARX, AAAS, KCTD17, PRDM8, and CRTC1 in FS brains as these genes are downregulated in Q84Pfs-Het brains and play a role in these movement and muscle coordination 43–49." (PMID 37398410, 2023).
epidermolysis bullosa simplex (5 papers, 2018 to 2025). Epidermolysis bullosa simplex (EBS) is a group of hereditary epidermolysis bullosa (HEB) disorders characterized by skin fragility resulting in intraepidermal blisters and erosions that occur either spontaneously or after physical trauma. "DST pathogenic variants cause either HSAN-VI or epidermolysis bullosa simplex phenotypes likely due to tissue-specific expression and functional roles of DST encoded isoforms." (PMID 40938507, 2025). "DST codes for the dystonin protein, involved in keratinocyte integrity and mutated in a specific subtype of Epidermolysis Bullosa simplex." (PMID 29963229, 2018). "Loss-of-function mutations in both DST-a and DST-b result in HSAN-VI, and loss-of-function mutations of DST-e result in the skin blistering disease epidermolysis bullosa simplex." (PMID 35942699, 2022). "Loss-of-function mutations in dystonin (DST) can cause hereditary sensory and autonomic neuropathy type 6 (HSAN-VI) or epidermolysis bullosa simplex (EBS)." (PMID 32482619, 2020).
cardiomyopathies (4 papers, 2010 to 2025). "Taken together, these data suggest that unidentified familial myopathies and/or cardiomyopathies caused by DST-b mutant alleles exist in all populations worldwide." (PMID 35942699, 2022). "Based on the results from our molecular analysis of hypertrophic markers, we hypothesized that the deficiency of dystonin in dtTg4 mice would lead to signs of cardiomyopathy at morphological and histological levels." (PMID 20209123, 2010).
epidermolysis bullosa (4 papers, 2013 to 2024). Epidermolysis bullosa (EB) is a group of genetic skin diseases that cause the skin to blister very easily. "Mutations of LAMA3, LAMB3, LAMC2, DST, and COL17A1 have been reported in heritable skin fragility disorders and epidermolysis bullosa (EB)." (PMID 36430582, 2022). "The Lamc2jeb junctional epidermolysis bullosa (EB) mouse model has been used to demonstrate that significant genetic modification of EB symptoms is possible, identifying as modifiers Col17a1 and six other quantitative trait loci, several with strong candidate genes including dystonin (Dst/Bpag1)." (PMID 37883475, 2023).
Sensory neuropathy (4 papers, 2011 to 2022). Peripheral neuropathy affecting the sensory nerves. "Dystonia musculorum is an inherited recessive sensory neuropathy, and is caused by loss-of-function mutations in the dystonin gene (DST), which encodes a cytoskeletal cross-linking protein." (PMID 30403723, 2018). "In mice, dystonin deficiency is associated with dystonia musculorum, an inherited sensory neuropathy that often leads to pre-weaning death." (PMID 22859963, 2012). "Because the Dst-b-specific nonsense mutation resulted in myopathy without sensory neuropathy, and mutant DST alleles with nonsense mutations in DST-b-specific exons exist, our data suggest that unidentified human myopathy may be caused by these DST-b mutant alleles." (PMID 35942699, 2022).
Alzheimer disease (3 papers, 2021 to 2026). A progressive, neurodegenerative disease characterized by loss of function and death of nerve cells in several areas of the brain leading to loss of cognitive function such as memory and language.
head and neck squamous cell carcinoma (3 papers, 2014 to 2021). A squamous cell carcinoma that arises from any of the following anatomic sites: lip and oral cavity, nasal cavity, paranasal sinuses, pharynx, larynx, and salivary glands. "The discovery that the alternative splicing of the dystonin (DST) gene (encoding for BPAG1) occurs in head and neck squamous cell carcinoma (HNSCC) provides a basis for the existence of cancer-specific BPAG1 isoforms." (PMID 29587367, 2018). "DST was reported to act as a tumor-specific alternative splicing factor in head and neck squamous cell carcinoma." (PMID 34211976, 2021).
hereditary sensory and autonomic neuropathy type 6 (3 papers, 2018 to 2020). "Of these, dystonin mutations link to the axonopathy HSAN6 (type 6 hereditary sensory and autonomic neuropathy)." (PMID 31706327, 2019).
colon cancer (2 papers, 2018 to 2021). "On the other hand, CIC, DST, KAT6B and NOTCH4 represent novel genes that may be implicated in the onset and/or development of colon cancer." (PMID 29844865, 2018).
Hereditary Sensory Autonomic Neuropathy (2 papers, 2016 to 2021). "DST mutations cause hereditary sensory neuropathy, possibly via Ca2+ dyshomeostasis, pathologic ER stress response induction, and subsequent sensory neuron apoptosis." (PMID 34035477, 2021).
lung adenocarcinoma (2 papers, 2018). A carcinoma that arises from the lung and is characterized by the presence of malignant glandular epithelial cells. "In lung adenocarcinoma, only the EAM gene ITGB1 and the desmosome gene DST significantly converged towards co-occurrence (p value = 0.021)." (PMID 29348685, 2018). "DST, FRG1B and BAGE2 are thus candidate driver genes for lung adenocarcinoma and good targets for follow-on experiments." (PMID 30541428, 2018).
Obesity (2 papers, 2025). Accumulation of substantial excess body fat. "Interestingly, dystonin was observed to be an important player in the autophagosome-endolysosome pathway, which may represent a link to obesity." (PMID 41225618, 2025).
asthma (1 paper, 2012). "We identified two novel variants in two genes, DST and MEF2A, that had high coverage and could potentially be risk, MEF2A, or protective, DST, asthma variants." (PMID 23046476, 2012).
autism (1 paper, 2018). Persistent deficits in social interaction and communication and interaction as well as a markedly restricted repertoire of activity and interest as well as repetitive patterns of behavior. "Nonetheless, among downregulated genes (adjusted p value < 0.002), interestingly enough, DST, a gene previously related with autism was found to be altered in this patient and also was found to be dysregulated in a mouse model for SMS syndrome." (PMID 29794985, 2018).
breast tumour (1 paper, 2019). "To test the possibility that the tumour suppressor effect of DST is endorsed by specific DST spliced variants, we searched for the DST isoform downregulated in breast tumour samples." (PMID 31882643, 2019). "However, we cannot exclude that the long BPAG1 isoforms also exhibit tumour suppressor effects in breast epithelial cells, as all DST isoforms are downregulated in breast tumour samples." (PMID 31882643, 2019).
clear cell renal cell carcinoma (1 paper, 2022). "In the clear cell renal cell carcinoma cohort, the DST, MED13 and ABCC6 gene mutation frequencies significantly differed among different low and high IP-score groups." (PMID 36700205, 2022).
colorectal cancer (1 paper, 2025). A primary or metastatic malignant neoplasm that affects the colon or rectum. "Furthermore, DST regulates cisplatin resistance in colorectal cancer through the PI3K/AKT pathway." (PMID 40228435, 2025).
endometriosis (1 paper, 2020). The growth of functional endometrial tissue in anatomic sites outside the uterine body. "Five genes (ANXA4, CDA, CDK10, DST, and HSP90AB1) from the catalogue were reported to be associated with endometriosis at two omics levels, for example ANXA4 gene at transcriptomics and ANXA4 at proteomics level." (PMID 32474803, 2020).
fibrosis (1 paper, 2025). the formation of excess fibrous connective tissue in an organ or tissue in a reparative or reactive process. "In summary, we found that a novel modified CTS, DST-3, was capable of treating BLM-induced fibrosis in C57BL/6 mice or TGF-β1-induced fibrosis in MRC5." (PMID 41155944, 2025).
hypertrophic cardiomyopathy (1 paper, 2010). A condition in which the myocardium is hypertrophied without an obvious cause. "Interestingly, dystonin-deficient hearts do display features of hypertrophic cardiomyopathy at the molecular level but not at the morphological level." (PMID 20209123, 2010).
invasive breast carcinoma (1 paper, 2012). A carcinoma that infiltrates the breast parenchyma. "Down regulation of DST and HTRA1 has been associated with progression to invasive breast cancer and was found in our data-set." (PMID 23236365, 2012).
lobular carcinomas (1 paper, 2007). "Several genes encoding proteins involved in actin, calcium and metal ion binding were downregulated (MYBPC1, DST, PIP, CA2), and some genes with the same function (BGN, ADAM12) were upregulated in lobular carcinomas." (PMID 17389037, 2007).